DEF8 (differentially expressed in FDCP 8 homolog)
Description:
Positively regulates lysosome peripheral distribution and ruffled border formation in osteoclasts. Involved in bone resorption.
Synonyms: FLJ20186
Tractability: PROTAC: ubiquitination databases record sites on it; its protein half-life has been measured.
Gene: Protein-coding gene on chromosome 16 (89,948,127 to 89,968,066, forward strand). Ensembl gene ENSG00000140995.
Subcellular location (Human Protein Atlas): Cytosol; Nucleoplasm
Gene Ontology:
Biological process: lysosome localization; positive regulation of bone resorption; positive regulation of ruffle assembly
Genetic constraint (gnomAD): Loss-of-function variants: 38 observed, 53.65 expected, observed/expected ratio (o/e) 0.71, 90% interval 0.55 to 0.93. The upper end of that interval is the gene's LOEUF score, 0.93, which puts it in group 3 of 6, group 1 being the genes least tolerant of losing a copy. Missense variants: 553 observed, 590.51 expected, observed/expected ratio (o/e) 0.94, 90% interval 0.87 to 1. Synonymous variants: 264 observed, 240.13 expected, observed/expected ratio (o/e) 1.1, 90% interval 0.99 to 1.22.
Homologues: Orthologues: chimpanzee DEF8 (99% identical), macaque DEF8 (99% identical), guinea pig DEF8 (94% identical), mouse Def8 (93% identical), dog DEF8 (90% identical), pig DEF8 (87% identical), rat Def8 (86% identical), tropical clawed frog def8 (81% identical), rabbit DEF8 (79% identical), zebrafish def8 (68% identical), Drosophila melanogaster DEF8 (34% identical), Caenorhabditis elegans Y56A3A.16 (27% identical). Paralogues in human: RUBCN (27% identical), PLEKHM1 (24% identical), PLEKHM3 (23% identical), RUBCNL (22% identical).
Diseases named in the same sentence as DEF8 in open-access papers:
DEF8 is named in the same sentence as 12 diseases in open-access papers, as found by Europe PMC text mining. Sharing a sentence is not in itself a finding about the gene and the disease. The quoted sentences say what the papers report.
melanoma (2 papers, 2023 to 2024). A malignant, usually aggressive tumor composed of atypical, neoplastic melanocytes. "For example, genes in cluster 2 (SPIRE2, SPATA2L), 3 (OCA2, DBNDD1, FANCA, GAS8) and 4 (URAHP, DEF8, CPNE7, MC1R) underlie the associations between melanoma and pigmentation traits." (PMID 38308491, 2024).
colonic adenomas (1 paper, 2023). "ElaC ribonuclease Z 2 (ELAC2) is primarily associated with prostate cancer, and MARCH6, along with ACSM2B, DEF8, DIS3L, and KCNA5 gene variants, have not been associated with colonic adenomas yet." (PMID 36765865, 2023).
Crohn disease (1 paper, 2013). A gastrointestinal disorder characterized by chronic inflammation involving all layers of the intestinal wall, noncaseating granulomas affecting the intestinal wall and regional lymph nodes, and transmural fibrosis. "Five genes (NME6 from the purine/thiopurine network, PLCB2 of the RAC1 network, and HVCN1, CTSS, and DEF8) correlated with the Harvey-Bradshaw index of Crohn’s disease activity." (PMID 23437289, 2013). "The expression levels of four genes identified by microarray screening (PLCB2, HVCN1, CTSS, and DEF8) and one purine/thiopurine related gene (NME6) correlated significantly with the clinical activity of Crohn’s disease." (PMID 23437289, 2013).
cancer (1 paper, 2020). A tumor composed of atypical neoplastic, often pleomorphic cells that invade other tissues. "DEF8, NDUFC2, GUSBP1, ARIH2, STX12 and HIST1H2BN were highly re-expressed (more than 100 folds) in either treatment of MV4-11, have not been previously discussed on their role in cancer except for HIST1H2BN." (PMID 32337016, 2020).
neurodegenerative disease (1 paper, 2023). A disorder of the central nervous system characterized by gradual and progressive loss of neural tissue and neurologic function. "A potential scenario for Def8's relevance for neuronal functionality and morphology is its role in aggregated protein clearance in the nervous system, a pathological hallmark of neurodegenerative diseases such as AD." (PMID 37816871, 2023).
Neurological disease (1 paper, 2023). "Furthermore, Neurological disease is one of the most enriched categories (p-value 5.55E−4–2.27E−6) linked to DEF8 interactome as predicted by IPA." (PMID 37816871, 2023). "These bioinformatic analyses suggest that DEF8 has a role in the autophagy pathway and may have a role in metabolic and neurological disorders." (PMID 37816871, 2023).
DEF8 also shares sentences with these, for which no sentence is quoted: adenoma (1 paper); Alzheimer disease (1); bone marrow failure (1); cutaneous squamous cell carcinoma (1); Fanconi anaemia (1); prostate carcinoma (1).